SPOP (speckle type BTB/POZ protein)
Diseases named in the same sentence as SPOP in open-access papers (continued):
Sharing a sentence is not in itself a finding about the gene and the disease.
ovarian carcinoma (7 papers, 2017 to 2025). A malignant neoplasm originating from the surface ovarian epithelium. "Speckle-type POZ protein (SPOP), an E3 ubiquitin ligase substrate-binding adaptor protein, was markedly downregulated in human ovarian cancer tissues, and its lower expression levels were associated with advanced cancer stages and malignancy." (PMID 34572373, 2021). "Therapies targeting the CUL3/SPOP complex-PD-L1 axis hold significant potential for improving treatment outcomes in ovarian cancer." (PMID 40521202, 2025). "Further investigation is required to discover the function of SUFU downregulation by SPOP in ovarian cancer." (PMID 34021128, 2021). "SPOP transfection was associated with decreased proliferation, colony formation, and enhanced apoptosis of OVCAR-3 ovarian cancer cells, while SPOP knockdown produced the opposite effects." (PMID 34572373, 2021). "Previous studies of our group have shown that SPOP protein with low expression level can promote proliferation and migration of ovarian cancer cells." (PMID 34131189, 2021). "Therefore, detection of SPOP in cells is of great value for the cytology study and prognosis of ovarian cancer." (PMID 34131189, 2021). "Finally, variants in the genes ROS1, NOTCH1, ALK, KMT2D, and SPOP have to our knowledge not previously been reported in ovarian cancer." (PMID 28611940, 2017). "Interestingly, low SPOP levels contributed to enhanced Hh signaling by modulating GLI1/2 expression, resulting in decreased apoptosis in ovarian cancer cell lines." (PMID 34572373, 2021). "In addition, we also observed a negative correlation between SPOP and SUFU accompanied by dysregulated SHH signaling in ovarian cancer." (PMID 34021128, 2021).
renal cell carcinoma (7 papers, 2019 to 2025). "Limited studies have shown that SPOP is overexpressed in human renal cell carcinoma (RCC) tissue." (PMID 36474188, 2022). "Studies have shown that SPOP is significantly upregulated in renal cell carcinoma (RCC) tissues at both the transcriptional and translational levels, and this upregulation was positively associated with cancer metastasis in patients with RCC." (PMID 31901237, 2020).
lung adenocarcinoma (6 papers, 2018 to 2026). A carcinoma that arises from the lung and is characterized by the presence of malignant glandular epithelial cells. "The critical roles of SPOP during the DDR upon exposure to exogenous DNA damage were also assessed in human lung adenocarcinoma cells." (PMID 33023230, 2020). "To test conservation of the function of SPOP in downregulating MyD88, we constructed expression vectors with SPOP of human and mouse origin and respectively transfected the plasmid into human lung adenocarcinoma cells (A549 cells) and CHO cells." (PMID 32365080, 2020). "The correlation analysis indicated that the C/EBPα and SPOP alterations were significantly positively correlated in lung adenocarcinoma (P < 8.9e−14) and squamous cell carcinoma (P < 2.3e−05)." (PMID 30607139, 2018). "(A, B) The expression of C/EBPα and SPOP in lung adenocarcinoma and lung squamous cell carcinoma has a downward trend compared with that in normal tissues." (PMID 30607139, 2018). "Based on the TCGA data, the expression of SPOP and C/EBPα in lung adenocarcinoma and lung squamous cell carcinoma has a downward trend compared with that in normal tissues." (PMID 30607139, 2018). "However, the precise role of SPOP in lung adenocarcinoma (LUAD) remains unclear, particularly in relation to its expression patterns, prognostic significance, and potential as a therapeutic target." (PMID 40657370, 2025).
bladder cancer (5 papers, 2019 to 2025). "Targeting this crosstalk may provide a promising therapeutic strategy for patients with bladder cancer harboring SPOP deficiency." (PMID 40521202, 2025). "For further verification, by transfecting wild-type or mutant LATS1 plasmids into 293T or bladder cancer cells and confirmed that mutation of SBC1 led to remarkable blockade of LATS1 degradation mediated by SPOP, while depletion of SBC2 had little effect." (PMID 37684641, 2023). "Furthermore, the transcription factor VEZF1 was found to directly activate SPOP transcription, and its overexpression suppressed these effects in bladder cancer cells." (PMID 40521202, 2025). "LATS1 interacted with the SPOP protein in bladder cancer cells." (PMID 37684641, 2023). "Next, we transfected HA-tagged SPOP at different concentrations into bladder cancer cells." (PMID 37684641, 2023). "These together suggest that the regulation of CYCLIN E1 stability by SPOP is cell line specific, and may be selectively occurs in some types of prostate and bladder cancer cell lines." (PMID 30237511, 2019). "All these indicate that SPOP regulates CYCLIN E1 stability in prostate and bladder cancer cell lines." (PMID 30237511, 2019). "We show here SPOP interacts with CYCLIN E1, selectively regulates its stability in prostate and bladder cancer cell lines, and regulates PCa tumorigenesis through CYCLIN E1 degradation." (PMID 30237511, 2019). "SPOP has been reported to function as a tumor suppressor in most tumors, and recent studies have shown that SPOP can mediate STAT3 degradation, thereby inhibiting bladder cancer progression." (PMID 41213915, 2025). "Therefore, to verify that SPOP was involved in the ubiquitylation and degradation of LATS1 in human bladder cancer cells, we first performed IP followed by mass spectrometric detection with LATS1 antibodies in T24 cells." (PMID 37684641, 2023). "Our data showed that SPOP regulates CYCLIN E1 stability specific in some prostate and bladder cancer cell lines, but not in the other tested cell lines." (PMID 30237511, 2019).
lymph node metastasis (5 papers, 2014 to 2022). "FOXA1 mutations were found in 3/8 (38%) lymph node metastases and in 1/23 (4%) CRPC metastases, whereas SPOP mutations were detected in 1/8 (13%) lymph node metastases and in 2/23 (9%) CRPC metastases." (PMID 29988112, 2018). "High SPOP expression is negatively correlated with lymph node metastasis, poor histological differentiation, and tumor malignancy according to TNM staging." (PMID 25204354, 2014). "Further correlation analysis revealed that SPOP expression was negatively related to lymph node metastasis, poor histopathologic differentiation and advanced TNM stages." (PMID 25204354, 2014). "It is notable that SPOP was negatively correlated with lymph node metastasis, poor histopathologic differentiation and advanced TNM stages, regardless of age and gender." (PMID 25204354, 2014). "Our observations indicate that all SPOP pathogenic lesions are associated with patients that have developed biochemical recurrence or lymph node metastasis, but they do not correlate with the most serious cases." (PMID 35347810, 2022).
metastatic prostate carcinoma (5 papers, 2020 to 2023). A carcinoma that arises from the prostate gland and has spread to other anatomic sites. "Clinical trials in men with metastatic prostate cancer found that SPOP mutations are associated with improved survival outcomes after ADT." (PMID 36776288, 2023). "However, recent clinical trials in men with metastatic prostate cancer found that SPOP mutations are associated with improved survival outcomes after ADT." (PMID 36776288, 2023). "Monitoring ZBTB38 expression level in tumours might thus be useful, in combination with other genetic alterations (i.e., SPOP/SPOPL), to target metastatic prostate cancer with doxorubicin-based therapies." (PMID 32365491, 2020).
prostatic intraepithelial neoplasia (5 papers, 2018 to 2025). "The next events include the dysregulation of ETS transcription factor, loss of NKX3.1, mutations of SPOP, and TMPRSS2–ERG fusion at the prostatic intraepithelial neoplasia (PIN) stage." (PMID 35163157, 2022).
diffuse large B-cell lymphoma (4 papers, 2020 to 2025). "This study planed to uncover the biological roles of epigenetic SPOP/CHAF1A axis in modulating tumor autophagy during Diffuse large B-cell lymphoma (DLBCL) tumorigenesis." (PMID 35773729, 2022).
melanoma (4 papers, 2017 to 2025). A malignant, usually aggressive tumor composed of atypical, neoplastic melanocytes. "To further determine how these cancer-derived mutations affect endogenous HDAC6 abundance, we generated a melanoma cell line (WM2664) stably expressing SPOP WT or cancer-derived mutants including F102C, W131G, F133L, as well as empty vector (EV) as a negative control." (PMID 28599312, 2017). "Cytokine profiling of SPOP-depleted human melanoma A2058 cells revealed increased expression of interferon-stimulated genes (ISGs), including IFIT1, CXCL10, and MX1, which was validated by RT-PCR." (PMID 41148213, 2025). "In a xenografted melanoma B16 tumor model, single-cell RNA-seq analysis demonstrated that SPOP inhibition induced the infiltration of immune cells associated with anti–PD-1 responses." (PMID 41148213, 2025). "Given that type I interferons and ISGs mediate tumor innate immune activation and recruit immune infiltrates, these findings indicate that SPOP depletion enhances tumor innate immunity to suppress melanoma growth." (PMID 41148213, 2025). "Here, we demonstrate that SPOP acts as an oncogene in melanoma by targeting the innate immune sensor STING for ubiquitination and degradation." (PMID 41148213, 2025). "In this study, we revealed that SPOP targeted the innate immune sensor STING for degradation in a CK1γ phosphorylation-dependent manner to promote melanoma growth." (PMID 41148213, 2025). "Analysis of the Tumor Immunotherapy Gene Expression Resource further showed that melanoma patients with high SPOP expression had poorer responses to anti–PD-1 therapy, likely due to reduced STING levels and lower tumor-infiltrating immune cells." (PMID 41148213, 2025). "Since SPOP inhibition stabilizes and activates STING, triggering IFN and ISG production, which could promote immune cell infiltration, we evaluated whether SPOP inhibitors enhance ICB efficacy in melanoma models." (PMID 41148213, 2025). "Here, pharmacological SPOP inhibition stabilizes and activates tumor STING, driving infiltration of CD4+, but not CD8+, T cells, thereby improving anti–PD-1 efficacy in B16 melanoma." (PMID 41148213, 2025). "We identified the E3 ligase SPOP as a suppressor of tumor immunity by promoting ubiquitination and degradation of the innate immune sensor STING in melanoma and RCC." (PMID 41148213, 2025). "SPOP inhibitors act as dual-function molecular glue degraders that stabilize and activate STING, boosting anti-melanoma immunity and enhancing responses to checkpoint and CAR-T therapies." (PMID 41148213, 2025). "SPOP depletion markedly enhanced ISD90-induced STING activation, as shown by increased pSTING, an effect reversed by SPOP reexpression in HMCB melanoma cells." (PMID 41148213, 2025). "SPOP loss consistently increased STING protein levels, but not those of cGAS, TBK1, or IRF3, across human melanoma (A2058, HMCB, and MeWo), mouse melanoma (B16), human RCC (A498, 786-o, and UMRC6), mouse RCC (Renca), and HEK293 cells." (PMID 41148213, 2025). "In this study, we focus on melanoma and RCC to determine whether SPOP regulates tumor immunity." (PMID 41148213, 2025). "Likewise, SPOP knockdown in mouse RCC Renca and melanoma B16 cells impaired in vitro growth." (PMID 41148213, 2025).
metastatic disease (4 papers, 2018 to 2025). "Missense mutations in SPOP (Speckle-type POZ protein) are the most common point mutations in PCa, occurring in 10% of primary and metastatic tumors." (PMID 30200539, 2018). "Our preclinical data suggest that SPOP inhibition may be effective in clinical settings where ERG is robustly expressed (e.g., neo-adjuvant setting or early metastatic disease)." (PMID 33531470, 2021).
non-small cell lung carcinoma (4 papers, 2019 to 2024). A group of at least three distinct histological types of lung cancer, including non-small cell squamous cell carcinoma, adenocarcinoma, and large cell carcinoma. "HS3ST1 has been found to promote tumor non-small-cell lung cancer progression by regulating SPOP/FADD/NF-κB pathway." (PMID 38173042, 2024). "SPOP has been reported to suppress tumorigenesis by inhibiting the NF-κB pathway in certain tumor types, indicating that this SPOP‒FADD‒NF-κB axis might represent a molecular mechanism underlying the role of FADD alteration in non-small-cell lung cancer." (PMID 31569512, 2019).
pancreatic cancer (4 papers, 2021 to 2025). "Hence, this manuscript is aimed at comprehensively estimating the expression profiles, immune cells, and genomic characteristics of SPOP in multiple cancers including pancreatic cancer and assessing the association of SPOP with infiltrating immune cells (TICs) in pancreatic cancer." (PMID 39074086, 2024). "In the same year, researchers have also found that SPOP functions as a tumor suppressor in pancreatic cancer, where it was found to be downregulated in most patients, with low expression levels correlating with poor prognosis." (PMID 40521202, 2025). "Since, the functional gene enrichment analysis suggested that SPOP involved in immune regulation in pancreatic cancer." (PMID 39074086, 2024). "The expression level of SPOP was significantly correlated to tumor-infiltrating immune cells (TICs) in pancreatic cancer." (PMID 39074086, 2024). "Then immunohistochemistry (IHC) was used to estimate the correlation between SPOP and tumor-infiltrating lymphocytes (TILs) in patients with pancreatic cancer." (PMID 39074086, 2024). "In our cohort of 32 paired patients, the protein expression level of SPOP was downregulated in pancreatic cancer (PAAD) compared with normal tissues (P < 0.0001)." (PMID 39074086, 2024). "Targeting the SPOP-NANOG axis presents a promising therapeutic strategy for pancreatic cancer." (PMID 40521202, 2025). "Our study uncovered the potential corrections in SPOP with TICs, suggesting that SPOP may act as a biomarker for immunotherapy in pancreatic cancer." (PMID 39074086, 2024). "Similarly samples from pancreas cancer with mutant SPOP had high levels of PD-L1, showing the role of SPOP in immune system invasion." (PMID 33906413, 2021). "Besides, our results clarified a statistically positive correlation between SPOP expression and TICs in the pancreatic cancer, which implied that SPOP could be predicted the potential efficiency of immunotherapy, and served as a biomarker of pancreatic cancer." (PMID 39074086, 2024). "Although SPOP has been considered as a tumor suppressor in pancreatic cancer by targeting NANOG, however, the potential immunological role of SPOP in pancreatic cancer have rarely been estimated holistically." (PMID 39074086, 2024).
renal carcinoma (4 papers, 2020 to 2025). A carcinoma arising from the epithelium of the renal parenchyma or the renal pelvis. "Only renal cancer presented up-regulation of SPOP expression in cancer tissue (RR 0.08, 95% CI 0.05–0.12, fix effect model)." (PMID 34838022, 2021). "It was reported that SPOP could promote the epithelial–mesenchymal transition of kidney, epithelial–mesenchymal transition in renal cancer epithelial cells, and promote the development of renal cancer." (PMID 37941785, 2023). "Notably, SPOP not only can be functionalized as a tumor suppressor by targeting androgen receptor for degradation, but also as an oncoprotein in renal cancer, resulting in activation of androgen receptor driven pathways." (PMID 34838022, 2021). "In HEK293 cells, SPOP overexpression results in the activation of the c-Jun N-terminal kinase (JNK) pathway, and up to 99% of renal cancer patients show an increased expression of SPOP, whereas in MM its expression is rather heterogeneous and its role in MM needs to be evaluated." (PMID 33327527, 2020). "However, renal cancer presented improved expression of SPOP in cancer tissue." (PMID 34838022, 2021). "This study collectively demonstrates that SPOP promotes the ubiquitination and degradation of LATS1, thereby enhancing renal cancer cell invasion." (PMID 40771930, 2025). "SPOP has been identified as a novel E3 ligase for LATS1 in ccRCC cells, with the E3 ubiquitin ligase Cullin3/SPOP mediating the stability of LATS1 through polyubiquitination, leading to its degradation in a degron-dependent manner in renal carcinoma." (PMID 40771930, 2025).
glioma (3 papers, 2020 to 2022). A benign or malignant brain and spinal cord tumor that arises from glial cells (astrocytes, oligodendrocytes, ependymal cells). "In detail, SPOP downregulation in adult gliomas has been associated with disease progression and has been positively correlated with mean tumour diameter, tumour grade and histological type." (PMID 35715818, 2022). "Conversely, overexpression of SPOP significantly suppressed glioma cell migration and invasion in vitro." (PMID 31901237, 2020). "The function of SPOP has also been reported in glioma and osteosarcoma." (PMID 31901237, 2020). "Furthermore, molecular studies found that SPOP was markedly downregulated in glioma samples compared to normal brain tissues, and low expression of SPOP displayed a potential for indicating poor prognosis in patients with glioma." (PMID 31901237, 2020).
head and neck squamous cell carcinoma (3 papers, 2024 to 2026). A squamous cell carcinoma that arises from any of the following anatomic sites: lip and oral cavity, nasal cavity, paranasal sinuses, pharynx, larynx, and salivary glands. "The results revealed that SPOP mRNA expression profiles correlated significantly with AJCC/UICC TNM (Tumor Node Metastasis) stage in patients with BRCA, COAD, ESCA, LUAD, Head and Neck squamous cell carcinoma (HNSC) and STAD." (PMID 39074086, 2024). "The speckle-type BTB/POZ protein (SPOP) is an E3 ubiquitin ligase adaptor typically considered a tumor suppressor, yet its role in head and neck squamous cell carcinoma (HNSCC) remains unclear." (PMID 41828504, 2026).
hepatoblastoma (3 papers, 2020 to 2024). Hepatoblastoma (HB) is a malignant hepatic tumor and is the most common pediatric liver cancer. "A previous study revealed using exome sequencing that SPOP was heterozygously mutated in one hepatoblastoma case and that it may normally play a tumor suppressive role in hepatoblastoma." (PMID 31901237, 2020). "SLC7A1 (solute carrier family 7 member 1), for example, could be a SPOP substrate and influence cell phenotypic via regulating arginine metabolism, as well as regulate the hepatoblastoma process." (PMID 37337170, 2023). "In hepatoblastoma (HB), SLC7A1, acting as a substrate of the tumor suppressor gene SPOP, modulates the progression of HB through the regulation of arginine metabolism, thereby offering a novel therapeutic target for HB." (PMID 38903179, 2024).